VEGFA (vascular endothelial growth factor A)
Diseases named in the same sentence as VEGFA in open-access papers (continued):
Sharing a sentence is not in itself a finding about the gene and the disease.
cancer (continued). "The activation of LDHA may become a new therapeutic target due to it promotes the invasion and metastasis of cancer cells 26, and VEGFA is the main driver of angiogenesis and vascular permeability." (PMID 35711827, 2022). "Indeed, relative to P2-blue, it emerges that P2-orange experienced more hypoxic conditions manifesting as higher cancer cell expression of VEGFA and necrotic regions." (PMID 36352222, 2022). "In addition, we investigated the relationship between FASN and immune checkpoint gene expression and found that FASN was significantly positively correlated with the immune checkpoint genes CD276 and VEGFA in as many as 27 cancer species." (PMID 36555243, 2022). "Similarly, the growth of cancer cells is prevented through the degradation of hypoxia-inducible factor 1 (HIF-1)-mediated vascular endothelial growth factor A. HIF-1 expression is vital for tumor growth and angiogenesis." (PMID 35682652, 2022). "VEGFA is one of the most important regulators of angiogenesis in a variety of cancers." (PMID 35941690, 2022). "VEGFA and its receptors’ signaling pathways could be an alternative to the hypoxia mechanism leading to cancer progression." (PMID 36230822, 2022). "Moreover, negative regulatory genes of cancer-immunity cycle (CIC) illustrated that immunosuppressors TGFB1, VEGFA, and CD274 (PDL1) were all positively correlated with risk-scores." (PMID 35222383, 2022). "In addition to the already-known targets, we further identified relevant cancer-associated genes; such as, FGFR1, VEGFA, WNT9A, and FZD4." (PMID 35132075, 2022). "Several studies have found that VEGFA is highly expressed in NPC cells and is associated with cell proliferation, invasion and metastasis, chemosensitivity, radiosensitivity, and other phenotypes of cancer cells." (PMID 36506508, 2022). "Doxycycline down-regulates vascular endothelial growth factor A (VEGF-A) expression which may also be connected to cancer proliferation and inflammation." (PMID 35237605, 2022). "By comparing their differentially expressed genes, EMT-like TSKs were dramatically enriched with ECM organization, proteoglycans in cancer, regulation of cell adhesion, and the VEGFA-VEGFR2 signaling pathway, representing more invasive properties compared with EMT-unlike TSKs." (PMID 35908020, 2022). "HIF-mediated transcription was observed in aggressive cancer cells and induced VEGFA expression." (PMID 35646655, 2022). "Aside from in vitro research, we then investigated the correlations between CEBPD, hsa-miR-429 and VEGFA expression and their associations with microvascular density and clinical aggressiveness in UBUC and UTUC cohorts comprised of cancer tissue samples from 295 and 340 patients, respectively." (PMID 35203290, 2022). "Thus, bevacizumab, a VEGFA inhibitor, is a promising agent, useful in overcoming both hypoxia and resistance in cancer therapy." (PMID 35562993, 2022). "CXC chemokines and VEGFA may promote cancer progression, and this could be through a potential interaction network." (PMID 36246978, 2022). "Vascular endothelial growth factor A (VEGFA) had worsened OS and increased cancer development." (PMID 36268283, 2022). "Although we have demonstrated that VEGFA silencing could attenuate migration, invasion, glucose consumption and lactate production of cancer cells, a study limitation should be taken into consideration." (PMID 35646922, 2022). "However, the specific functions of VEGFA-evoked autophagy in regulating cancer progression have yet to be investigated in depth." (PMID 34982945, 2022). "In addition, we found that macrophage subpopulations (clusters 1, 5, 7, 8, and 9) from cancer tissues expressed a certain number of immunosuppressive genes, such as VEGFA, MMP14, MMP19, S100A2, APOE, HMOX1, SLAMF7, SIRPα, LAG3 and IL18." (PMID 36158683, 2022).
cancer (continued). "Cancer-associated fibroblasts (CAFs) can inhibit both the innate and adaptive antitumor immune response by secreting numerous chemokines and cytokines, such as TGF-β, IL-6, IL-8, IL-13, CXCL12, CXCL14, and VEGFA." (PMID 35646893, 2022). "VEGFA also plays a role in various cancer types and angiogenesis in general." (PMID 36140706, 2022). "In addition, in supratentorial (ST) EPN, NOTCH1 expression was associated with cancer stem cell (CSC) markers, VEGFA and L1CAM, and the ST_EPN_RELA subtype showed the activation of selected key members of the Notch signaling pathway (NOTCH1, JAG1, JAG2, HES4)." (PMID 36293188, 2022). "VEGFA products in cancer have been studied with their interaction in different signaling pathways, such as STAT3 (activator of transcription 3), KRAS (Kirsten rat sarcoma virus), and MAPK, mediated by protein kinase B (PI3K) and regulated by ERK, among other factors." (PMID 35205327, 2022). "Moreover, it is thought that vascular endothelial growth factor A (VEGF-A)—a proangiogenic molecule produced from cancer cells—is a meaningful factor in the development of an immunosuppressive microenvironment." (PMID 36010854, 2022). "Given that VEGFA is a critical factor for the angiogenesis in cancers, the ability of HUVECs tube formation was determined in the mock-CEBPD-overexpressing BFTC909 and TCCSUP cells treated with miRNA mimic negative control or hsa-miR-429 mimic or/and hsa-miR-429 inhibitor." (PMID 35203290, 2022). "VEGFA plays a key role in angiogenesis and invasion of several different cancer cell types." (PMID 33535182, 2021). "Targeting VEGFA signaling have been reported to be a promising strategy in human cancers." (PMID 33962397, 2021). "Lymphocyte-specific protein tyrosine kinase (LCK) phosphorylates Tyrosine-342 of FOXP3 and upregulates its expression resulting in decreased Matrix metalloproteinase 9 (MMP9), S-phase kinase-associated protein 2 (SKP2), and Vascular endothelial growth factor A (VEGF-A) levels in cancer cells." (PMID 33614551, 2021). "Interestingly, VEGFA pre-mRNA alternative splicing changes in many types of cancer and alternative splicing in general are known to be affected by RNA polymerase II (RNAPII) activity." (PMID 34316716, 2021). "BCL2, VEGFA and IL-6 were found to be enriched in pathways in cancer." (PMID 33510225, 2021). "In addition, VEGFA is an important target for cancer therapy, and VEGF inhibitors such as bevacizumab are now widely used." (PMID 34925533, 2021). "Finally, VEGFA +157 enhancer promotes VEGFA isoforms that have been shown to promote endothelial cell migration and thus cancer." (PMID 34316716, 2021). "In cancer-bearing mice, cancer tissues modulate the microenvironment in the distal organ by releasing various cytokines, including vascular endothelial growth factor A (VEGFA), TNF, transforming growth factor-β (TGFβ), and G-CSF, to prepare for subsequent cancer metastasis." (PMID 34674757, 2021). "Since CAFs promote cancer progression via secreting cytokines and growth factors, and our study showed that CAFs secreted VEGFA, we explored whether VEGFA play a role in CAFs mediated metastasis." (PMID 34977016, 2021). "Additionally, cancer cells promote monocyte recruitment through the release of chemotactic signals such as VEGFA, CCL2, CXCL12, semaphorin 3A (SEMA3A)." (PMID 34680425, 2021). "It was described that VEGFA mediated signaling influenced the function of immune cells in cancer." (PMID 33916904, 2021). "Similarly to TTP, BRF1 binds to mRNAs through a tandem zinc finger domain with a double zinc finger motif, it promotes the mRNA decay of various cancer-related transcripts (e.g., VEGFA), and its expression is reduced in several cancers." (PMID 34502337, 2021).
cancer (continued). "VEGFA is one of the key regulators of angiogenesis, it is responsible for many angiogenesis-related diseases including cancer, it also mediates the effect of miRNAs in cancer." (PMID 34977016, 2021). "VEGFA has several alternative splicing isoforms with different roles in cancer progression." (PMID 34316716, 2021). "In addition, hnRNP L has been found to regulate VEGFA mRNA translation and induce apoptosis of cancer cells, thereby inhibiting the development of cancer." (PMID 32915499, 2020). "We previously reported that VEGFA expression is modulated by ID4 in cancer cells." (PMID 32054109, 2020). "VEGFA and Rho signaling deregulation also promotes cancer progression and metastasis." (PMID 32377503, 2020). "In summary, our results suggest that POLR1D may act as a potential driver gene in the 13q12.2 amplification and may affect cancer progression by increasing the expression of VEGFA and EREG." (PMID 32087735, 2020). "The intersection of differentially expressed genes (DEG) and our list of candidate genes, resulted in 12 elements including cancer associated genes (NRAS, MYC, and VEGFA), circadian drug targets (SOD2 and CES2) and core-clock and ECCN genes (AHR, CREB1, CSNK2A1, NFIL, NPAS2, NR1D1, and PER3)." (PMID 32295075, 2020). "Potential effect of IL-4 and IL-13 (250 ng/mL, 24 h) on the expression of genes encoding proteins relevant for cancer development by facilitating angiogenesis (HIF1A and VEGFA), inflammation (PTGS2, NOS2, CCL2), and metabolic reprogramming (GLUT1, ODC1, NOS2) was evaluated." (PMID 32512917, 2020). "Moreover, analysis of clinical datasets revealed that a higher BTG3/VEGFA expression ratio correlates with improved patient survival in a number of cancer types." (PMID 33311481, 2020). "However, many scholars reported MR as a tumor suppressor gene in various cancer types, including Warburg effect inhibition, VEGFA dysfunction, and EMT 22-24." (PMID 33193899, 2020). "In this study, we demonstrated that the metabolite secretions of GG, M3 and YYC-3 suppressed VEGFA expression and secretion, and limited the expression and secretion levels of MMP2 and MMP9; suggesting that the inhibition of VEGF-MMP signalling pathway is suppressing cancer cell metastasis." (PMID 33228670, 2020). "For instance, vascular endothelial growth factor A (VEGF-A) can produce both proangiogenic and antiangiogenic isoforms; thus, a shift in the splicing machinery towards the production of the former enhances angiogenesis in cancer." (PMID 31861708, 2019). "For instance, the overexpression of VEGFA in aggressive oral squamous cell carcinoma (OSCC) may serve a vital prognostic factor for this kind of cancer." (PMID 31921137, 2019). "To test whether the VEGFA-STAT3-KLF4-CDKN1A signal axis was accidental in HNSCC, we studied the cancers with high expression of VEGFA based on TCGA database." (PMID 31198634, 2019). "Therefore, the use of different strategies to regulate VEGFA/VEGFR2 signaling pathway can be very beneficial for cancer therapy." (PMID 31217787, 2019). "Therefore, understanding the mechanisms of VEGFA is critical to establishing better strategies for cancer treatment." (PMID 31673071, 2019). "Recent clinical studies also support the role of VEGFA in anti-cancer immunity." (PMID 31766690, 2019). "However, activation in certain disease states including infection and cancer can induce Wnt-dependent vascular endothelial growth factor A (VEGF-A) expression followed by angiogenesis." (PMID 31681283, 2019). "VEGFA is a well-known cytokine that stimulates capillary proliferation in carcinoma." (PMID 31886201, 2019). "The specific role of EPRS in cancer is not well understood but its role as a translational silencer of angiogenic factor VEGFA (vascular endothelial growth factor A) indicates that EPRS may influence tumorigenesis." (PMID 29596499, 2018). "VEGFA is also believed to directly increase the metastatic potential of cancer cells." (PMID 30533316, 2018).
cancer (continued). "Meanwhile, by interacting with miRNAs, circRNAs also have the potential of impacting a variety of signaling pathways in cancers, such as vascular endothelial growth factor A (VEGFA) signaling pathway, large tumor suppressor kinase 1 (LATS1), Src family tyrosine kinases (SFKs) and so on." (PMID 29416705, 2018). "Recent data also demonstrated that concurrent neutralization of VEGFA and Ang-2 promotes the development and deployment of antitumor immunity in mouse models of cancer, expanding the rationale for trials combining Ang-2–directed therapy with checkpoint inhibitors." (PMID 30701027, 2018). "This label means that the co-function module may dysregulate the gene VEGFA to contribute to the development of the 26 cancers (C) with the probability of 77%." (PMID 28340554, 2017). "Thus miR-452 repression is required not only for VEGFA-dependent Slug upregulation in vitro, but also for increased cancer metastasis in vivo." (PMID 28504716, 2017). "For the non-cancer diseases (N), only two genes (VEGFA and MMP2) can be mapped to this pathway." (PMID 28340554, 2017). "Interestingly, the expression of VEGFA protein was abolished in most cancers (90%), while the protein was expressed in 80% normal lungs." (PMID 29137669, 2017). "Recent studies reported that miR-150 could regulate HIF-1α and VEGFA by targeting in many kinds of cancers." (PMID 28399173, 2017). "AECII cultures derived from normal lungs or cancers both expressed VEGFA at a similar level, suggesting that the in vitro conditions might have modified the expression of VEGFA proteins." (PMID 29137669, 2017). "With regard to the CAF model, patient-derived normal and according cancer-associated fibroblasts revealed a conserved gene expression, defined by increased transcript levels of ACTA2, COL1A1, TNC, VEGFA and ALDH1A3, with concomitant decreased expression of CAV1, CD44 and VIM in CAFs." (PMID 28372546, 2017). "Interestingly, VEGFA protein expression was restored in primary cultures of AECIIs derived from both normal lungs and cancers, proving that these cells retained their potential to produce VEGFA proteins." (PMID 29137669, 2017). "Next, to determine the function of ADAM9 in vascular remodeling, we measured the level of secreted VEGFA in conditioned media of cancer cells by ELISA and found lower concentrations of VEGFA in ADAM9 knockdown cell media compared to that in control (shGFP) cell media." (PMID 29118335, 2017). "Recent studies indicated that both HIF-1α and VEGFA could be regulated by miRNAs in many kinds of cancers." (PMID 28399173, 2017). "VEGFA could created a perivascular niche for TSLCs by stimulating angiogenesis in a paracrine manner, and directly stimulated cancer stemness and renewal." (PMID 28163656, 2017). "Similarly, the angiogenesis-mediated protein (VEGFA) and the antiapoptotic marker (Bcl2) were expressed in all cancer tissues." (PMID 29104726, 2017). "VEGFA is a key gene during the development of vessels during organogenesis or cancer." (PMID 29137669, 2017). "EOC tends to give rise to abnormal vasculature characterized by leaky and immature vessels that are conducive to cancer cell metastasis, and high levels of VEGFA can transform normal, functional ovarian epithelium into ascites-producing cancers by enhancing vascular permeability." (PMID 27050277, 2016). "SNAI1, SNAI2, ZEB2, and VEGFA have been reported as miR-203 targets related to cancer invasion." (PMID 26882562, 2016). "In contrast, cancers exhibiting little ZEB1 showed diminished VEGFA expression and vascularization." (PMID 26882471, 2016). "Current anti-VEGF (Vascular Endothelial Growth Factor A) therapies to treat various cancers indiscriminately block VEGF function in the patient resulting in the global loss of VEGF signaling which has been linked to dose-limiting toxicities as well as treatment failures due to acquired resistance." (PMID 27992500, 2016).
cancer (continued). "Furthermore, VEGFA-induced activation of mTor signaling cascades also promoted cancer cell growth through cyclinD1 and CDK4 activation." (PMID 26308848, 2015). "The anti-cancer effect of EXD compound interact with VEGFA, emodin, has been reported." (PMID 26191080, 2015). "Thus, DIG-MSK was a strong inhibitor of VEGF pathway; but, contrasting with other anti-angiogenic drugs, DIG-MSK showed a dual effect inhibiting both VEGFA expression in cancer cells and VEGFR1 and VEGFR2 expression in ECs." (PMID 26536461, 2015). "This is especially important for cancer cell lines with high levels of VEGFA secretion." (PMID 26452217, 2015). "Inhibitors of VEGFA-mediated angiogenesis are already in the clinic for cancer treatments." (PMID 26089392, 2015). "As angiogenesis has a critical role in the metastatic process, which is the primary cause of mortality in cancer patients, the down-regulation of chemokine (C-C motif) ligand 2 (CCL2) and vascular endothelial growth factor A (VEGFA), subsequent to AhR knockdown was deemed of high significance." (PMID 24932473, 2014). "VEGFA is a potent angiogenic factor that plays essential roles in cancer." (PMID 23536895, 2013). "Vascular endothelial growth factor-A (VEGF-A), plays essential roles in vascular development in embryogenesis, in the maintenance of the normal function of the adult vasculature and in neovascularisation associated with cancer, eye and other diseases." (PMID 23409021, 2013). "Therefore, understanding how VEGFA expression is regulated will facilitate development of novel strategies to effectively target it for cancer treatment." (PMID 23536895, 2013). "As VEGFA is known to promote angiogenesis during tumor progression in a variety of cancers, we next assessed whether inhibition of VEGFA also blocked angiogenesis in ERMS in vivo." (PMID 24009521, 2013). "Reducing M2 macrophage characteristics systemically may provide advantages to cancer patients because they express much lower levels of TGFβ, VEGFA, VEGFC, MMP-9, and MMP-1." (PMID 23667623, 2013). "VEGFA production is enhanced in hypoxia and is therefore found in growing tissues such as cancer." (PMID 22348394, 2012). "Therefore, out of the assayed microRNAs, miR-361-5p seems most likely to contribute to elevated VEGFA mRNA levels in this type of cancer." (PMID 23166713, 2012). "Patients with higher VEGFA mRNA levels showed a tendency towards shorter cancer-specific survival." (PMID 22895562, 2012). "This may be due in part to the lower rate of VEGFA found in MSI compared to MSS CRCs which may reduce the level of metastatic spread in MSI cancers." (PMID 23110075, 2012). "Furthermore, cancer-cell-derived TGF-b release proangiogenic vascular endothelial growth factor A (VEGFA) from the myofibroblasts in esophageal squamous cell to regulate angiogenesis." (PMID 22482059, 2012). "We therefore wondered whether the 3′-conserved region of the VEGFA 3′-UTR contains additional MREs that may contribute to VEGFA dysregulation in cancers." (PMID 23166713, 2012). "Besides its inhibitory effect on endothelial cells, THL inhibited hypoxia-induced HIF-1α and vascular endothelial growth factor-A expression in cancer cells." (PMID 20429953, 2010). "In this study we focused on determining the mechanism by which the UPR regulates VEGFA expression, as VEGFA is the best characterized stimulator of angiogenesis and represents a therapeutic target for treating cancer as well as several ischemic, infectious and inflammatory disorders." (PMID 20824063, 2010). "Interestingly, despite this pro-angiogenic phenotype, VEGFA expression was reduced in PAK4KO cancer cells, indicating that alternative angiogenic mechanisms may compensate for VEGFA downregulation." (PMID 41294859, 2025).